TGFBR2 (transforming growth factor beta receptor 2)
Diseases named in the same sentence as TGFBR2 in open-access papers (continued):
Sharing a sentence is not in itself a finding about the gene and the disease.
airway allergy (1 paper, 2021). "Moreover, the transcription factor FOXO1, which was recently described to be essential for Th9 cell differentiation and IL-9 production, was clearly reduced upon Tgfbr2 ablation, correlating with reduced airway allergy." (PMID 35069535, 2021).
anal carcinoma (1 paper, 2013). "The absence of Tgfbr2 may also predispose the mice to genital and anal cancers." (PMID 24124460, 2013).
aneurysmal disease (1 paper, 2019). "It was reported that heterozygous kinase-inactivating mutations in genes coding for either transforming growth factor-β receptor subunit (TGFBR1 or TGFBR2) cause Loeys–Dietz syndrome, characterized by a highly penetrant and aggressive aneurysmal disease." (PMID 31045834, 2019).
arteriovenous malformations (1 paper, 2012). "Thus, loss of Tgfbr2 does not appear to be involved in the development of arteriovenous malformations during organogenesis, in agreement with a previous report." (PMID 22745736, 2012).
arthrogryposis (1 paper, 2021). A rare, non-progressive congenital disorder characterized by multiple joint contractures which are present at birth. "Specific limb alterations compatible with arthrogryposis were observed in at least three further LDS patients, two of them bearing a variant in the TGFBR2 gene." (PMID 35052370, 2021).
autoimmune myocarditis (1 paper, 2024). Autoimmune myocarditis is an autoimmune disease that affects the heart. "Experimental autoimmune myocarditis (EAM) was induced in the LysM-Cre × R26-stop-EYFP × Tgfbr2-fl/fl transgenic mice showing impaired TGF-β signalling in the myeloid lineage and the LysM-Cre × R26-stop-EYFP control mice." (PMID 38891767, 2024).
Axenfeld-Rieger's anomaly (1 paper, 2005). "The abnormalities presented by Tgfbr2-mutant mice are characteristic of the disorders found in patients with Axenfeld-Rieger's anomaly." (PMID 16403239, 2005).
basal cell carcinoma (1 paper, 2021). A carcinoma involving the basal cells. "KEGG analysis also highlights several pathways associated with disease including “basal cell carcinoma” (Wnt6, Gli2, Wnt10a) and “htlv-i infection” (Smad4, Wnt10a, Prkacb, Wnt6, Tgfbr2) in M. spretus." (PMID 34794440, 2021).
benign papillomas (1 paper, 2015). "Conversely, morphological and biochemical features of benign papillomas were enhanced in HRasG12V; Tgfbr2-null tumor masses in the absence of ETS2." (PMID 26590320, 2015).
Brain atrophy (1 paper, 2025). Partial or complete wasting (loss) of brain tissue that was once present. "Moreover, brain atrophy was reduced in the EC-specific overexpression of the Tgfbr2 gene group." (PMID 40667795, 2025).
brain injury (1 paper, 2025). Acute and chronic (see also brain INJURIES, CHRONIC) injuries to the brain, including the cerebral hemispheres, CEREBELLUM, and brain STEM. "Therefore, understanding the role of miR-34b in regulating TGFBR2 in the context of brain damage could provide valuable insights into potential therapeutic targets for mitigating brain injury." (PMID 39129166, 2025).
Castleman disease (1 paper, 2023). Castleman disease (CD) is a benign lymphoproliferative disorder that may present as a localized or multicentric form. "In Castleman disease, improper ETS1, PTPN6, TGFBR2, DNMT3A, and PDGFRB genes cause the appearance of symptoms." (PMID 36766791, 2023).
cervical diseases (1 paper, 2020). "There are few reports on the correlation between TGFBR2 and cervical diseases." (PMID 32993576, 2020).
cervical dysplasia (1 paper, 2017). "In summary, our study verified the correlations of TGFBR2 and hTERT in vitro and suggests that TGFBR2 and hTERT expression may be used as a diagnostic biomarker for cervical dysplasia and carcinoma." (PMID 28195144, 2017).
cervical squamous cell carcinoma (1 paper, 2017). A squamous cell carcinoma arising from the cervical epithelium. "This implies that somatic alterations in TGFBR2, CREBBP, and SMAD4 may be cervical squamous cell carcinoma-specific, although E7-driven expression effects in the TGFβ pathway may still play a role in carcinogenesis in other HPV-positive cancers." (PMID 28771191, 2017).
Charcot-Marie-Tooth disease type 1A (1 paper, 2019). Charcot-Marie-Tooth disease type 1A (CMT1A) is a type ofinherited neurological disorder that affects the peripheral nerves. "Muscle biopsy and genetic testing regarding Charcot-Marie-Tooth disease type 1A (CMT1A), Friedrichs ataxia (trinucleotide repeat in FXN), Loeys-Dietz syndrome (TGFBR1, TGFBR2) and Ehler Danlos syndrome type IV (COL3A1) were all normal as well as the karyotype of lymphocytes (46,XX)." (PMID 31053103, 2019).
cholesteatoma (1 paper, 2024). A pathologic process characterized by the proliferation of keratinizing squamous epithelium resulting in the accumulation of keratin and cells in the middle ear and/or mastoid. "Combined with the results of this study, we suppose that TGFBR2 could be a promising target in the drug development strategies of cholesteatoma." (PMID 38890701, 2024).
clear cell ovarian cancer (1 paper, 2016). "The most single SNP association was seen with TGFBR2 and clear cell; the T allele in rs3773636 was associated with a 21% increased risk of clear cell ovarian cancer (OR = 1.21, 95% CI = 1.10-1.33, p = 0.0001)." (PMID 27533245, 2016).
cleft palate (1 paper, 2025). Cleft palate is a fissure type embryopathy that affects the soft and hard palate to varying degrees. "Herein, we utilized the power of mouse genetics and precision genome editing to directly test if a candidate human variant in TGFBR2 was a new causal variant for isolated micrognathia and cleft palate." (PMID 40489498, 2025).
Corneal opacity (1 paper, 2024). A reduction of corneal clarity. "Consistent with a protective effect of Tgfbr2 heterozygosity, fewer eyes having corneal opacity were excluded in the Col4a1+/G1344D;Tgfbr2+/– group than in the Col4a1+/G1344D;Tgfbr2+/flox group." (PMID 38717426, 2024).
cutaneous squamous cell carcinoma (1 paper, 2016). "Here, the authors demonstrate that inactivating driver mutations in TGFBR1 and TGFBR2 occur in vemurafenib-induced and sporadic cutaneous squamous cell carcinomas." (PMID 27558455, 2016). "Using targeted sequence analysis and whole-exome sequencing (WES), we identify frequent mutation in both transforming growth factor-β (TGFβ) type 1 receptor (TGFBR1) and TGFβ type 2 receptor (TGFBR2) genes in human primary cutaneous squamous cell carcinoma (cSCC) samples." (PMID 27558455, 2016).
developmental delay (1 paper, 2018). "The third report documented a TGFBR2 deletion identified by array CGH in a patient with microcephaly, mild dysmorphic features, and global developmental delay without any other features of LDS." (PMID 30219046, 2018).
diaphragmatic hernia (1 paper, 2018). A congenital or acquired weakness or opening in the diaphragm which allows abdominal contents to protrude into the chest cavity; congenital diaphragmatic hernias are caused when the embryonic diaphragm fails to fuse. "The peak of this TGFβ gradient is at E13.5 and the anterior diaphragmatic hernia seen in the Tagln-Cre:Tgfbr2 knockout is probably a representation of a halt in diaphragmatic development at this stage." (PMID 29483576, 2018).
DiGeorge syndrome (1 paper, 2006). "Moreover, it has been suggested that deletion of Tgfbr2 in NCCs leads to other phenotypic features reminiscent of those seen in the velocardiofacial/DiGeorge syndrome (VCF/DGS) caused by a deletion of the so called DiGeorge critical region (DGCR) on chromosome 22q11." (PMID 17078885, 2006).
esophageal adenocarcinoma (1 paper, 2023). A malignant tumor with glandular differentiation arising predominantly from Barrett mucosa in the lower third of the esophagus. "Knockdown of TGFBR2 impairs TGF-β signaling induced by SPARC in esophageal adenocarcinoma cells." (PMID 37569556, 2023).
Feingold syndrome type 2 (1 paper, 2018). Feingold syndrome type 2 (FS2) is a rare inherited malformation syndrome characterized by skeletal abnormalities and mild intellectual disabilities similar to those seen in Feingold syndrome type 1 (FS1) but that lacks the manifestations of gastrointestinal atresia and short palpebral fissures. "In the mouse model for Feingold syndrome type 2, using genetic and pharmacological interventions, we have demonstrated that the upregulation in TGF-β signaling due to derepression of Tgfbr2, a direct target of multiple miR-17-92 miRNAs, plays the causal role." (PMID 29636449, 2018).
glucocorticoid resistance (1 paper, 2023). "The fluctuation of TGFβ1 and TGFBR2 allowed us us to speculate that such configuration may favor TNFα pro-inflammatory signaling to induce an acute form of glucocorticoid resistance (GCR)." (PMID 37301958, 2023).
Headache (1 paper, 2014). Cephalgia, or pain sensed in various parts of the head, not confined to the area of distribution of any nerve. "As a result, we recognized totally 7 possible causing genes (CALCA, TGFBR2, TNF, ESR1, EDNRA, KCNK18, and MTHFR) of headache in the top 10 genes." (PMID 24991551, 2014).
hemiplegic migraine (1 paper, 2025). "This study presents novel evidence linking hemiplegic migraine (HM) to rare variants in genes previously implicated in cerebral SVD, including LRP1, COL4A1, and TGFBR2." (PMID 40869943, 2025).
Immunodeficiency (1 paper, 2022). Failure of the immune system to protect the body adequately from infection, due to the absence or insufficiency of some component process or substance. "In addition to the TGFBR2 variants, rare variants in other immunodeficiency genes were also found in the four cases reported here." (PMID 36672844, 2022).
invasive carcinoma (1 paper, 2020). A carcinoma that is not confined to the epithelium, and has spread to the surrounding stroma. "Mutations in SMAD4 and TGFBR2 are frequently restricted to invasive carcinoma, while RNF43 alterations are largely in non-invasive lesions." (PMID 32796935, 2020).
Kaposi's sarcoma (1 paper, 2025). A malignant neoplasm characterized by a vascular proliferation which usually contains blunt endothelial cells. "This alteration silences tumor suppressor genes such as p16INK4a, TGF-β type II receptor (TbetaRII/TGFBR2), PDZ-LIM domain-containing protein 2 (PDLIM2), and CDH13, fostering unchecked cellular proliferation characteristic of Kaposi’s sarcoma." (PMID 40589575, 2025).
large-cell lung carcinoma (1 paper, 2009). "Loss of the tumour suppressor TGFBR2 expression is seen in many cancers with microsatellite instability and deleted in large-cell lung carcinoma." (PMID 19662092, 2009).
laryngeal tumors (1 paper, 2020). "Additionally, TGFBR2 was mutated at a higher frequency in our cohort (12.9%) compared to primary laryngeal tumors in TCGA (2.8%)." (PMID 33105726, 2020).
leukocytosis (1 paper, 2021). "A previous study demonstrated that TGFBR2 expression in epididymal DCs is crucial for immunotolerance to sperm in mice epididymis, the absence of which exhibits an immune response against sperm resulting in severe epididymal leukocytosis." (PMID 34113669, 2021).
lung squamous cell carcinoma (1 paper, 2024). "Additionally, a study showed that the absence of TGFBR2 promotes the progression of lung squamous cell carcinoma (LUSC), which is also a common type of NSCLC." (PMID 39364312, 2024).
malignant intestinal tumors (1 paper, 2016). "Although Tgfbr2 inactivation alone does not cause tumor-related changes, Tgfbr2 conditional knockout mouse models have indicated that Tgfbr2 inactivation in the intestinal epithelium accelerates the development of malignant intestinal tumors in combination with mutations in Apc, Kras, or Pten." (PMID 27835699, 2016).
mesothelioma (1 paper, 2009). A usually malignant and aggressive neoplasm of the mesothelium which is often associated with exposure to asbestos. "Interestingly, array analysis showed that estrogen suppresses TGFBR2 gene in estrogen sensitive tumours, that could indicate a role of estrogen in mesothelioma as well." (PMID 19662092, 2009).
metastatic prostate carcinoma (1 paper, 2021). A carcinoma that arises from the prostate gland and has spread to other anatomic sites. "Similarly, it has been reported that genetic polymorphism in the promoter region of TGFBR2 gene coding TGF-βRII was associated with Gleason score and risk of early relapse after ADT among patients with both non-metastatic and metastatic prostate cancer." (PMID 34113577, 2021).
Microglossia (1 paper, 2023). Decreased length and width of the tongue. "For example, mesenchymal-specific deletion of the TGFBR2 gene in TGFβ signaling and loss of KiF3a and intraflagellar proteins in Shh signaling lead to microglossia and aglossia, respectively." (PMID 37680190, 2023).
Micrognathia (1 paper, 2025). Developmental hypoplasia of the mandible. "Thus, it is more likely that this Tgfbr2 variant is not a causal allele for cleft palate or micrognathia leading to palate disruption in mammals despite the deep conservation and in silico predicted pathogenicity." (PMID 40489498, 2025).
middle ear cholesteatoma (1 paper, 2024). "The interaction network analysis of the two most upregulated miRNAs (hsa-miR-21-5p and hsa-miR-142-5p) and the three most downregulated miRNAs (hsa-miR-508-3p, hsa-miR-509-3p, and hsa-miR-211-5p) identified TGFBR2, MBNL1, and NFAT5 as potential key target genes in middle ear cholesteatoma." (PMID 38890701, 2024). "The interaction network of the the 2 most upregulated (hsa-miR-21-5p and hsa-miR-142-5p) and 3 most downregulated (hsa-miR-508-3p, hsa-miR-509-3p and hsa-miR-211-5p) miRNAs identified TGFBR2, MBNL1, and NFAT5 as potential key target genes in middle ear cholesteatoma." (PMID 38890701, 2024).
mucinous carcinoma (1 paper, 2016). "However, the mice exhibiting distinct morphological characteristics induced by Tgfbr2 inactivation, such as deep invasiveness and mucinous carcinoma, was a more convincing tool for identifying changes in gene expression induced by Tgfbr2 inactivation." (PMID 27835699, 2016).
oligodendroglioma (1 paper, 2019). A well-differentiated (WHO grade II), diffusely infiltrating neuroglial tumor, typically located in the cerebral hemispheres. "Variants in tumor associated genes not typically associated with oligodendroglioma were also found, such as missense variants in TET1 (NM_030625:c.4399G>A; p.Glu1467Lys) and TGFBR2 (NM_003242:c.426G>C; p.Glu142Asp as well as a frameshift variant in ARID1A (NM_006015:c." (PMID 31217899, 2019).
pancreatitis (1 paper, 2009). Inflammation of the pancreas. "S100A4+ DCs were implicated in the pathogenesis of AIP by demonstrating the presence of DCs that had undergone Cre-mediated Tgfbr2 recombination in pancreata from Tgfbr2fspKO mice, and by induction of pancreatitis in wild-type mice through transfer of DCs from Tgfbr2fspKO mice." (PMID 19625278, 2009).
penile cancer (1 paper, 2019). A primary or metastatic malignant neoplasm that affects the penis. "TGFBR2 was also predicted as one of the 47 candidate driver genes targeted by multiple miRNAs, the expressions of which were altered in penile cancer samples compared with normal penile tissue." (PMID 31842336, 2019). "Furthermore, TGFB3 and TGFBR2 were found within the top pathways involving miRNA-targeted genes disrupted in penile cancer." (PMID 31842336, 2019).
primary biliary cholangitis (1 paper, 2017). Primary biliary cholangitis (PBC) is a chronic and slowly progressive cholestatic liver disease of autoimmune etiology characterized by injury of the intrahepatic bile ducts that may eventually lead to liver failure. "Interestingly, dominant negative TGFBR2 mice has been verified would develop serological and histological features resembling human primary biliary cholangitis." (PMID 28886078, 2017).
primary effusion lymphoma (1 paper, 2021). A large B-cell lymphoma located in the body cavities, characterized by pleural, peritoneal, and pericardial fluid lymphomatous effusions and that is always associated with human herpes virus-8 (HHV-8). "Transcription repression via CpG DNA hyper-methylation of p16INK4a (CDKN2A), the TGF-beta type II receptor (TbetaRII, TGFBR2), and PDZ-LIM domain-containing protein 2 (PDLIM2) promoters have been detected in KSHV-infected primary effusion lymphoma (PEL) lines." (PMID 34307191, 2021).
prostatic hyperplasia (1 paper, 2017). "These Tgfbr2 knockout data confirmed that increased TGF‐β activity in the stroma enhances recruitment of nestin+ cells for prostatic hyperplasia." (PMID 28191756, 2017).
retinal degeneration (1 paper, 2022). Degeneration of the retina. "We recently showed that TGFβ receptor type 2 (Tgfbr2) is upregulated in retinal neurons and Müller cells during retinal degeneration." (PMID 35269767, 2022).
Rotavirus infection (1 paper, 2016). Infection with any of the rotaviruses. "A latest research reported that up-regulated miR-142-5p inhibits TGF-β-induced apoptosis via targeting TGFBR2 and SMAD3 in rotavirus infection model." (PMID 27683030, 2016).
serous ovarian cancer (1 paper, 2022). "We performed the qRT-PCR analysis of TGFβ components (TGFB1, TGFB2, TGFBR1, TGFBR2), Wnt5A/ROR1/ROR2, and Hippo-related genes (YAP1, TAZ, CCN1, and CCN2) in serous ovarian cancer subtypes (LGSOC, HGSOC, BLSOC) compared to the normal ovary." (PMID 35053353, 2022).
skin tumour (1 paper, 2023). "Loss of Tgfbr2 coupled with Trp53loss/mutational activation (LPT mice) resulted in skin tumour formation with long latency (median survival = 429 days)." (PMID 37626054, 2023).
thyroid (1 paper, 2021). "Furthermore, we analyzed the mRNA expression pattern of TGFB1, TGFBR1, and TGFBR2 in malignant and benign thyroid tissues." (PMID 33905626, 2021).
thyroid cancer (1 paper, 2023). "We validated the downregulation of SNAI2, SOX4, and TGFBR2, three targets never investigated in thyroid cancer cells, and of HMGA2, a miR-2 04-5p target previously identified in the lab (unpublished results), in TPC-1 and BCPAP cells following miR-204-5p overexpression." (PMID 37445942, 2023).
thyroid nodule (1 paper, 2021). A small circumscribed mass in the THYROID GLAND that can be of neoplastic growth or non-neoplastic abnormality. "First, in this study, we aimed to investigate the role of TGFB1, TGFBR1, and TGFBR2 SNPs in the susceptibility to thyroid nodules malignancy and their correlation to clinical and anatomopathological characteristics." (PMID 33905626, 2021). "On the other hand, TGFBR2 was downregulated in all histological types analyzed and was not able to differentiate thyroid nodules." (PMID 33905626, 2021).
unstable angina (1 paper, 2023). "We also compared the haplotype frequency of TGFBR2 rs6785358 and rs9838682 in unstable angina and the control group." (PMID 36672663, 2023).
uterine tumors (1 paper, 2023). "We profiled the data from uterine tumors deposited to the cBioPortal of Cancer Genomics for mutations of the TGFβ signaling pathway and identified several mutations in TGFβ-related receptors (TGFBR1, TGFBR2, ACVR1B, ACVR1C, ACVR2A, ACVR2B) and transcription factors (SMAD2, SMAD3, SMAD4)." (PMID 36906706, 2023).